CP (ceruloplasmin)
Diseases named in the same sentence as CP in open-access papers (continued):
Sharing a sentence is not in itself a finding about the gene and the disease.
Obesity (continued). "We demonstrate that ceruloplasmin is a novel adipokine, which is produced and secreted at increased rates in obesity." (PMID 24676332, 2014). "The influence of obesity on plasma levels and secretion of ceruloplasmin from subcutaneous adipose tissue was also investigated." (PMID 24676332, 2014). "Its secretion and expression are increased in obesity and adipose ceruloplasmin is a major contributor to the circulating ceruloplasmin level." (PMID 24676332, 2014). "In addition to neurodegeneration, obesity and steatosis have been reported in ceruloplasmin-KO mice, highlighting that ceruloplasmin is essential for Cu and Fe homeostasis." (PMID 38389896, 2024). "Therefore, we believe that ceruloplasmin is secreted in EVs at an increased rate during the development of obesity." (PMID 36830957, 2023). "Moreover, we found ceruloplasmin protein to be elevated in EVs released from adipose tissue under conditions of obesity and lipid hypertrophy, especially in visceral and brown fat depots." (PMID 36142750, 2022). "Thus, we found an imbalance of the pro- and antioxidant blood system in IBS with diarrhea and obesity, as evidenced by high levels of 8-isoprostane and ceruloplasmin." (PMID 34621378, 2021). "The study has also shown that ceruloplasmin, socio-economic indices, multiparity, pregnancy-induced hypertension, obesity and twin pregnancy are not risk factors for PPCM in the study area." (PMID 25853263, 2015). "Our estimates suggest that adipose tissue in obesity contributes with up to 22% to the circulating levels of ceruloplasmin and this secretion explained as much as 45% of the inter-individual variation in plasma ceruloplasmin in both non obese and obese subjects." (PMID 24676332, 2014). "Therefore, we hypothesize that ceruloplasmin is secreted in EVs in a higher proportion during the development of obesity." (PMID 36142750, 2022). "In obese animals, batosomes are enriched with proteins involved in signal transduction, cell communication, the immune response, inflammation, thermogenesis, and as obesity biomarkers including UCP1, Glut1, MIF, annexin A6, CD14, and ceruloplasmin." (PMID 36142750, 2022). "Thus, relatively low basal CP-AMPAR surface expression in combination with low basal AMPAR transmission may leave more “room” for the extrasynaptic insertion of CP-AMPARs following JF diet in obesity-prone compared with obesity-resistant males." (PMID 32731252, 2021). "Consequently, the identification of new adipokines in visceral adipose tissue vesicles from patients with obesity, and in EVs released from adipocytes with lipid hypertrophy, such as DDP4, mimecan, and ceruloplasmin, is also of interest." (PMID 36830957, 2023). "Thus, in obesity, batosomes are enriched with proteins involved in signal transduction, cell communication, the immune response, inflammation, thermogenesis, and potential obesity biomarkers including UCP1, Glut1, MIF, and ceruloplasmin." (PMID 36142750, 2022). "However, it is still controversial that Cu and ceruloplasmin are related to clinical outcomes in patients with NAFLD and obesity." (PMID 35741222, 2022). "We observed a significant induction in the levels of C3, CP enzyme, growth factor IGFBP4, and cytokine CXCL10 and interferon signaling-related genes including (IFNβ, ISG15, MX2 and OASL2), some of which have been recognized for their role either in obesity or inflammation." (PMID 33672392, 2021). "Since expression and secretion of some adipokines are differentially regulated in different fat depots, we do not know whether ceruloplasmin expressed and released from other depots may display other correlations with obesity." (PMID 24676332, 2014).
COVID-19 (25 papers, 2020 to 2026). A disease caused by infection with severe acute respiratory syndrome coronavirus 2. "In a very recent trial, the administration of CP within 9 days after the onset of COVID-19 symptoms reduced the risk of disease progression leading to hospitalization." (PMID 36611352, 2022). "The study supports the theory that patients with COVID-19 may have had co-infections caused by intracellular agents, i.e., MP and CP, during the first wave of pandemic in 2020." (PMID 36014055, 2022). "Age-associated changes in copper handling—including altered CP dynamics and impaired hepatic copper export—could therefore amplify COVID-19 severity by simultaneously weakening antiviral immunity and increasing vulnerability of metabolically active cells to copper-driven injury." (PMID 41516398, 2026). "Ceruloplasmin can act as an acute phase protein, being raised in inflammatory environments and has been shown to correlate with COVID-19 severity." (PMID 41557029, 2026). "Elevated levels of oxidative damage markers, such as MDAs, and reduced levels of ceruloplasmin were observed in our cohort of HD patients with moderate pre-infection nutritional deficiencies, suggesting that oxidative stress may play a significant role in the chronicity of COVID-19 sequelae." (PMID 38804402, 2024). "This gene was detected in 75% of COVID-19 CP-Kpn isolates, 76.5% of Madrid-CARB-ES-19 isolates, and 50% of CP-Kpn ICU-CARB-ES-19 isolates." (PMID 36671308, 2023). "Early, specific lectin pathway activation marker MASP-1/C1-INH complex, and C4d, a marker of common CP and LP activation, are elevated in COVID-19 when compared to healthy controls (HC)." (PMID 37051252, 2023). "More CP-Kpn COVID-19 isolates produced OXA-48 (60/84, 71.4%) and VIM-1 (18/84, 21.4%) than KPC (8/84, 9.5%)." (PMID 36671308, 2023). "The present study is important because it reports WGS analysis of CP-Kpn isolates colonizing or infecting seriously ill COVID-19 patients at the height of the pandemic in a region and at a time when healthcare services were extremely stressed." (PMID 36671308, 2023). "Albeit within the reference range, the levels of ALB were significantly lower, but CP were significantly higher in COVID-19 patients as compared to healthy controls." (PMID 36514048, 2022). "For these reasons, we decided to determine Cu and CP in relation to biomarkers of Se status in serum of patients with COVID-19, and to test their value for predicting survival odds." (PMID 34072977, 2021). "This notion is supported by a relatively unchanged Cu status in COVID-19 during the hospital stay, as observed both in the analysis of full blood in the study from Wuhan, and in our present analysis of serum Cu and CP in German patients." (PMID 34072977, 2021). "This study characterises changes in total serum Cu and CP concentrations, as biomarkers of Cu status, of patients with COVID-19 in relation to survival and disease progression during hospitalisation." (PMID 34072977, 2021). "In this work, we prepared a VP-IVIg from plasma of donors immunized with the BNT162b2 (Pfizer-BioNTech) anti-COVID-19 vaccine and compared its in vitro efficacy and safety with those of a similar CP-IVIg formulation." (PMID 35047966, 2021). "The univariate Cox analysis highlighted that 7 genes (including MRC1, CP, ITGA5, SNCA, HARS1, ENPP1, and PLAU) were significantly (p < 0.05) associated with CHOL/COVID-19." (PMID 34176789, 2021). "Furthermore, WGS data on COVID-19 isolates of CP-Kpn were directly compared with a pre-pandemic Spanish national collection of representative CP-Kpn isolates collected a few months before the start of the pandemic." (PMID 36671308, 2023). "However, we were not able to detect any differences in circulating markers of oxidative stress between the two groups of ARDS patients, but total antioxidant status and ceruloplasmin (a copper-containing ferroxidase) were reduced in COVID-19." (PMID 37408073, 2023).
COVID-19 (continued). "The present study has been undertaken to evaluate two aspects: (i) the possible co-infection of MP and CP in COVID-19 by the serological assessment of specific antibodies; and (ii) the possible role of both MP and CP as cofactors worsening COVID-19 clinical manifestations and outcomes." (PMID 36014055, 2022). "Our results suggest that the lectin pathway is activated in COVID-19 patients, with higher levels of the specific LP activation marker MASP-1/C1-INH complex, and the joint LP/CP marker C4d in more severe cases." (PMID 37051252, 2023). "The analysis included 85 non-duplicate CP-Kpn isolates from COVID-19 patients admitted to ICUs in five hospitals in Madrid." (PMID 36671308, 2023). "Albeit without statistical significance, levels of AGP, HP, and CP also increased but A2MG decreased in COVID-19 severity-dependent manner." (PMID 36514048, 2022). "When compared to controls, COVID-19 patients independently on their disease severity had lower plasma levels of ALB (by 42%) but significantly higher levels of AGP (by 2.4-fold), AAT (by 1.9-fold), CP (by 1.4-fold), HP (by 3.8-fold), and hs-CRP (by 52-fold)." (PMID 36514048, 2022). "When COVID-19 patients were segregated into subgroups, amongst the patients with a moderate disease, strong correlations were found between AAT and AGP (r = 0.91, p < 0.001), HP (r = 0.79, p < 0.01), hs-CRP (r = 0.72, p < 0.01), and CP (r = 0.89, p < 0.01)." (PMID 36514048, 2022). "When compared to controls, COVID-19 patients had significantly lower concentrations of ADAMTS13 and albumin (ALB) but higher M30, M65, α1-acid glycoprotein (AGP), α1-antitrypsin (AAT), ceruloplasmin (CP), haptoglobin (HP), and high-sensitivity C-reactive protein (hs-CRP)." (PMID 36514048, 2022). "Moreover, COVID-19 patients with diffuse and severe pneumonia also presented significant volumes of GGO, CP/LO and consolidation." (PMID 33658944, 2021). "Similarly, elevated levels of copper and ceruloplasmin, a copper transport protein, concentrations were found in surviving COVID-19 patients compared to healthy control or non-survivors indicating regulation of copper metabolism during COVID-19 infection." (PMID 36765106, 2023). "As per the independent prognostic and survival analyses, few of the important differentially expressed genes, including MRC1, CP, ITGA5, SNCA, HARS1, ENPP1, and PLAU may function as potent biomarkers for screening and characterizing different stages of CHOL patients with COVID-19." (PMID 34176789, 2021). "However, in severe COVID-19 patients the strongest positive correlations were found only between plasma levels of ACT and SAA, hs-CRP and AAT, and between CP and AAT, and negative correlations between HP and ACT as well as between HP and ALB." (PMID 36514048, 2022).
anemia (24 papers, 2005 to 2025). A reduction in the number of red blood cells, the amount of hemoglobin, and/or the volume of packed red blood cells. "Persistent anaemia after 4 weeks of iron and erythropoietin therapy requires further evaluation for other possible contributing factors, such as copper, ceruloplasmin or vitamin B12 deficiency, and appropriate treatment." (PMID 33514942, 2021). "Furthermore, consumption of the HFe diet caused cardiac hypertrophy, anemia, low serum and tissue copper levels and decreased circulating ceruloplasmin activity." (PMID 27537180, 2016). "Indeed, in absence of ceruloplasmin activity, iron accumulates in the liver causing anemia." (PMID 27729845, 2016). "Several clinical conditions, including renal failure and anemia of inflammation, are known for reasons to increase serum copper due to elevated serum ceruloplasmin." (PMID 36520275, 2023). "It has also been shown that downregulation of iron-regulated genes, including heparin, ceruloplasmin, transferrin, and transferrin receptors, disrupts the systemic iron homeostasis, leading to anemia in patients with HCC." (PMID 33685417, 2021). "Persistent anaemia after 4 weeks of iron and EPO therapy requires further evaluation for other possible contributing factors, such as copper, ceruloplasmin or vitamin B12 deficiency, followed by appropriate treatment." (PMID 33514942, 2021). "Ablation of HEPH and CP globally induces significant iron accumulation in these tissues, and leads to dramatically lower plasma iron and anemia." (PMID 29883959, 2018). "Beyond the effects and mechanisms of CKD anemia, other aspects associated with iron metabolism could be investigated using this model as a platform for the analysis of copper deficiency on iron metabolism through ceruloplasmin or even other iron metabolism related genetic mutations." (PMID 29659573, 2018). "If CP was indispensable for iron export from recycling macrophages, one would expect more pronounced anemia and even higher sTfR concentrations." (PMID 20801540, 2010). "Prasad and colleagues reported several cases of patients with sickle cell anemia who received 150 mg zinc/day and consequently showed low plasma copper, low ceruloplasmin, leukopenia, and anemia." (PMID 20617034, 2010). "Therefore, the positive relationship between circulating Cu concentration and anemia in this study probably mainly resulted from a common link, the inflammatory process, and were often observed in lung cancer patients ceruloplasmin alterations." (PMID 33375477, 2020). "Absence of ceruloplasmin (CP) in plasma in combination with mild anemia, hypoferremia, and hyperferritinemia is a diagnostic finding." (PMID 20801540, 2010). "TM was remarkably nontoxic when ceruloplasmin was lowered to 10–20% of baseline levels for up to 17 months of treatment, and the only drug-related toxicity observed was mild anemia, which was easily reversible with adjustment of the TM dose to bring the ceruloplasmin level to the desired target." (PMID 16277669, 2005). "Fe deficiency precedes anemia and several deleterious systemic effects because, when Fe levels are low, copper is absorbed mainly through the DMT1, and the role of copper in iron deficiency is to stimulate iron mobilization from stores by ceruloplasmin synthesis." (PMID 36840264, 2023). "That indicated such increase of TF and CP was not the result of inflammatory or anaemia but a phenomenon unique to PAB." (PMID 26099594, 2015). "However when iron stores are depleted – even when anemia is still not present – ceruloplasmin-levels are lower than in subjects with sufficient iron." (PMID 39506866, 2024). "Furthermore, profound anemia, neutropenia, and virtually absent serum copper and ceruloplasmin levels together with elevated zinc levels were diagnosed." (PMID 20617034, 2010).
anemia (continued). "Abnormal laboratory parameters include: decreased transferrin; ceruloplasmin; increased ferritin (non-specific, > 800 ng/mL); mixed hyperbilirubinaemia; low aminotransferases; low factors V and VII (< 10% of normal); thrombocytopenia, anaemia and increased alpha-fetoprotein (> 200 ng/mL)." (PMID 21092086, 2010).
lung carcinoma (21 papers, 1992 to 2024). "Expression of CP is significantly upregulated and associated with clinicopathological stage, disease occurrence, and poor outcomes in lung cancer patients." (PMID 38339384, 2024). "Numerous studies have reported a positive association between serum CP levels and carcinogenesis, tumor stage, and recurrence in cancers like pancreatic cancer, oral cancer, lung cancer, leukemia, and Hodgkin’s lymphoma." (PMID 38339384, 2024). "Ceruloplasmin (Cp) is known as a glycoprotein associated with malignancy in many cancers, including lung cancer and breast cancer." (PMID 35954297, 2022). "In conclusion, these results indicate that CP expression is elevated in lung cancer patients and higher levels of CP expression are associated with a shorter survival time." (PMID 32708433, 2020). "Consistently, H1563 cancer cells also expressed elevated levels of CP, we thus selected this lung cancer cell line to investigate the role of CP by a loss-of-function mode." (PMID 32708433, 2020). "Taken together, these results suggest that upregulation of ceruloplasmin, lipocalin 2 and perioston are associated with development of lung cancer, and correlated with repression of GPRC5A in NSCLC." (PMID 28088789, 2017). "CP levels were measured in sera from a cohort of lung cancer patients harboring the Kras mutation and healthy controls." (PMID 26133466, 2015). "In a study in Finland, high serum ceruloplasmin concentrations during the years prior to diagnosis were associated with an increased risk of cancer, especially with lung cancer." (PMID 24592197, 2014). "The elevated risk of lung cancer at high concentrations of serum ceruloplasmin persisted after further adjustment for several potential confounding factors such as serum levels of vitamins A and E and selenium." (PMID 1739632, 1992). "The smoking-adjusted relative risk of lung cancer among men was 4.3 (95% confidence interval (CI) = 1.8-10.6) in the highest quintile of serum ceruloplasmin as compared with that in the lowest quintile." (PMID 1739632, 1992). "This demonstrated that high CP expression could be positively associated with death related events and shows that the CP protein acts as a potential oncogenic factor, leading to lung cancer progression and poor clinical outcomes." (PMID 32708433, 2020). "Moreover, the incidence of cancer was reported to be positively associated with serum ceruloplasmin (CP) levels; the association was found to be strongest for lung cancer and other cancers related to smoking." (PMID 26133466, 2015). "The serum CP levels were elevated in lung cancer, colon carcinoma, epithelial ovarian cancer, and correlated with invasiveness of cancer cells, while in adrenocortical and hepatocellular carcinoma, the expression levels of CP were down-regulated." (PMID 36845727, 2023). "In lung cancer cells, silencing ceruloplasmin enhanced the iron concentration and upregulated the activity of PHD1/2 to induce the hydroxylation of HIF-2." (PMID 34413268, 2021). "High levels of ceruloplasmin are correlated not only with disease occurrence and invasiveness but also with worse outcomes in patients with lung cancer." (PMID 34413268, 2021). "Serum total SOD activity and SOD1, SOD2, albumin, CRP, and ceruloplasmin concentrations were determined in lung cancer patients (n = 190) and control subjects (n = 52)." (PMID 34832849, 2021). "The levels of miR-145-5p expression were different in the CL1-0, CL1-5, H1299, H1435 and H1563 cell lines and negatively correlated with CP expression in five lung cancer cell lines, with an R2 value of 0.6854 (p = 0.0419)." (PMID 32708433, 2020). "The current study demonstrates that a loss of miR-145-5p is critical for the pro-tumor function of CP, by increasing tumor angiogenesis in lung cancer." (PMID 32708433, 2020). "The current study provides evidence that the upregulation of CP caused by a loss of miR-145-5p reduces HIF-2α degradation and leads to lung cancer angiogenesis." (PMID 32708433, 2020).